TECR (trans-2,3-enoyl-CoA reductase)
Description:
Involved in both the production of very long-chain fatty acids for sphingolipid synthesis and the degradation of the sphingosine moiety in sphingolipids through the sphingosine 1-phosphate metabolic pathway. Catalyzes the last of the four reactions of the long-chain fatty acids elongation cycle. This endoplasmic reticulum-bound enzymatic process, allows the addition of 2 carbons to the chain of long- and very long-chain fatty acids/VLCFAs per cycle. This enzyme reduces the trans-2,3-enoyl-CoA fatty acid intermediate to an acyl-CoA that can be further elongated by entering a new cycle of elongation. Thereby, it participates in the production of VLCFAs of different chain lengths that are involved in multiple biological processes as precursors of membrane lipids and lipid mediators. Catalyzes the saturation step of the sphingosine 1-phosphate metabolic pathway, the conversion of trans-2-hexadecenoyl-CoA to palmitoyl-CoA.
Synonyms: TER; GPSN2; SC2; MRT14
Tractability: Antibody: UniProt predicts a signal peptide or a membrane-spanning region. PROTAC: ubiquitination databases record sites on it; its protein half-life has been measured.
Target class: Enzyme; Oxidoreductase
Gene: Protein-coding gene on chromosome 19 (14,517,085 to 14,565,988, forward strand). Ensembl gene ENSG00000099797.
Subcellular location: Endoplasmic reticulum membrane
Subcellular location (Human Protein Atlas): Endoplasmic reticulum
Pathways (Reactome):
Metabolism: Synthesis of very long-chain fatty acyl-CoAs
Gene Ontology:
Molecular function: protein binding; very-long-chain enoyl-CoA reductase activity; very-long-chain fatty acyl-CoA dehydrogenase activity; oxidoreductase activity, acting on the CH-CH group of donors; trans-2-enoyl-CoA reductase (NADPH) activity
Biological process: fatty acid elongation; sphingolipid metabolic process; very long-chain fatty acid biosynthetic process; long-chain fatty-acyl-CoA biosynthetic process; fatty acid biosynthetic process; lipid metabolic process
Cellular component: endoplasmic reticulum; endoplasmic reticulum membrane; nucleus
Genetic constraint (gnomAD): Loss-of-function variants: 19 observed, 51.5 expected, observed/expected ratio (o/e) 0.37, 90% interval 0.26 to 0.54. The upper end of that interval is the gene's LOEUF score, 0.54, which puts it in group 2 of 6, group 1 being the genes least tolerant of losing a copy. Missense variants: 313 observed, 412.39 expected, observed/expected ratio (o/e) 0.76, 90% interval 0.69 to 0.83. Synonymous variants: 168 observed, 165.97 expected, observed/expected ratio (o/e) 1.01, 90% interval 0.89 to 1.15.
Gene-disease validity (ClinGen):
ClinGen rates the evidence that TECR causes each of these diseases.
intellectual disability (autosomal recessive): Limited.
Homologues: Orthologues: guinea pig TECR (97% identical), mouse Tecr (96% identical), tropical clawed frog tecr (90% identical), chimpanzee TECR (89% identical), rat Tecrl2 (88% identical), zebrafish tecrb (85% identical), dog TECR (76% identical), zebrafish tecra (75% identical), macaque TECR (69% identical), Drosophila melanogaster Sc2 (54% identical), Caenorhabditis elegans art-1 (53% identical). Paralogues in human: TECRL (51% identical), SRD5A2 (23% identical), SRD5A1 (20% identical).
Diseases named in the same sentence as TECR in open-access papers:
TECR is named in the same sentence as 15 diseases in open-access papers, as found by Europe PMC text mining. Sharing a sentence is not in itself a finding about the gene and the disease. The quoted sentences say what the papers report.
mental retardation (2 papers, 2024 to 2025). "In humans, a missense mutation of P182L in TECR causes mental retardation." (PMID 38224948, 2024).
amyotrophic lateral sclerosis (1 paper, 2024). Amyotrophic lateral sclerosis (ALS) is a neurodegenerative disease characterized by progressive muscular paralysis reflecting degeneration of motor neurons in the primary motor cortex, corticospinal tracts, brainstem and spinal cord. "A more comprehensive analysis indicates that upregulated proteins (ELOVL5, ELOVL7, TECR, HSD17B4, ACSL1, HACD2, and CBR4) are significantly enriched within the pathways of oxidative phosphorylation and metabolic pathways pertinent to amyotrophic lateral sclerosis." (PMID 39335340, 2024).
autosomal recessive intellectual disability (1 paper, 2012). "Mutations in two of them, CC2D1A and TECR, were recently reported to be responsible for non-syndromal, autosomal recessive intellectual disability." (PMID 22419660, 2012).
colon cancer (1 paper, 2023). "Gene expression analysis of CRC using GEO dataset GSE20931 showed that the expression of ELOVL5, FADS2, HSD17B12, and trans-2,3-enoyl-CoA reductase (TECR), the enzymes involved in PUFA elongation and desaturation, were significantly increased in colon cancer samples compared to the normal tissue." (PMID 36970499, 2023).
tumor (2 papers, 2023 to 2024). "In addition, we found seven other genes recurrently affected by HBV integration in tumour tissue samples: ECE1, EVI5L, KIF13B, MTX1P1, PLXND1, TECR and USP24." (PMID 37400627, 2023).
TECR also shares sentences with these, for which no sentence is quoted: infection (7 papers); bacterial infection (3); COVID-19 (3); cancer (2); E. coli infection (1); fungal infection (1); geographic atrophy (1); gram-negative bacterial infections (1); Lymphadenopathy (1); virus infection (1).